EPO (erythropoietin)
Diseases named in the same sentence as EPO in open-access papers (continued):
Sharing a sentence is not in itself a finding about the gene and the disease.
Stroke (continued). "A case-control study in the United States, after adjusting for multiple confounding variables, revealed that patients treated with EPO had a 30% greater risk of stroke than those not treated with EPO." (PMID 41244199, 2025). "This exploratory finding may provide evidence for the potential use of UCB + EPO combination therapy for neurological recovery following stroke." (PMID 41456040, 2025). "In recent years, a potent neuroprotective agent, erythropoietin (EPO), has been demonstrated to enhance the permeability of astrocyte AQP4 and might directly lower the risk of astrocyte swelling in stroke and other brain disorders." (PMID 39944892, 2025). "Recently, a retrospective study revealed that a lower baseline response to erythropoietin can predict death, nonfatal myocardial infarction and nonfatal stroke." (PMID 41244199, 2025). "Moreover, the erythropoietin regimen was switched from a high dose to a lower dose owing to potential safety concerns raised by the US Food and Drug Administration (FDA) based on an erythropoietin multicenter stroke study." (PMID 40491611, 2025). "Additionally, the benefits of EPO were examined in a human randomized controlled trial involving stroke patients with cerebral hypoperfusion." (PMID 39764293, 2024). "We suggest that performing that MBH and EPO therapy first in patients with an acute stroke episode, followed by considering additional bypass surgery during a stable phase, could be a safe and effective treatment strategy." (PMID 39764293, 2024). "Therefore, a deeper understanding regarding the role of EPO, specifically in ischemic stroke, is required to improve recovery and brain repair process after stroke." (PMID 38302546, 2024). "Furthermore, we demonstrated that EPO dampened stroke-induced activation of TAK1 and the inflammasomes along with their downstream cascade." (PMID 34628598, 2022). "EPO might induce neurogenesis in neuropsychiatric disorders and neurological diseases, such as stroke." (PMID 35897720, 2022). "In conclusion, our data indicate that monocytic TAK1 is crucially involved in the regulation of the inflammasomes in the brain after stroke and that EPO conveyed neuroprotection after stroke might be mediated via an EPO/TAK1/inflammasome axis." (PMID 34628598, 2022). "In addition, we demonstrated that EPO mitigated stroke-induced activation of TAK1 and the inflammasomes along with their downstream cascade, which was not evident after Mi/MΦ TAK1 deletion." (PMID 34628598, 2022). "The subacute reperfusion phase of 72 h after stroke was chosen on the basis of our preliminary data, which showed a significant reduction in infarct volumes after this period upon three administrations of EPO." (PMID 34628598, 2022). "(iii) Is the EPO-mediated neuroprotection after stroke conveyed via an EPO/TAK1/inflammasomes axis?" (PMID 34628598, 2022). "Finally, both in vivo and in vitro studies show that EPO is able to increase oligodendrogenesis and remyelination after stroke." (PMID 33790864, 2021). "Moreover, it has been shown that the blockade of EPOR in the CNS leads to impairments in neural cell proliferation and survival during embryonic development, and in post-stroke neurogenesis in adult brain, further confirming EPO’s role in neurogenesis." (PMID 33790864, 2021). "Erythropoietin has been shown to protect neurons from ischemic damage, suppress neuronal apoptosis and necroptosis by attenuating cytokine production and inflammation, reduce astrocyte edema in stroke, and promote brain angiogenesis after focal ischemia." (PMID 34276338, 2021). "The basis for the EPO stroke trial was the finding of EPO distribution into CSF." (PMID 33207605, 2020). "Longer treatment duration - over many weeks - may ultimately enhance the benefit of EPO for neuroprotection and neuroregeneration also after stroke." (PMID 32546125, 2020).
Stroke (continued). "Most experimental studies focused on EPO treatment within the first hours following vessel occlusion, simulating the unpredictable situation clinicians face in the emergency department or in the stroke unit after sudden onset of a neurological deficit." (PMID 33312715, 2020). "We hypothesized that EPO administered prior to transient MCAO exerts its neuroprotective properties in the early phase of stroke primarily via secondary neuroprotection by reduction of cerebral edema." (PMID 33312715, 2020). "A recent meta-analysis confirmed the protective role of exogenously administered EPO in stroke." (PMID 32733466, 2020). "EPO administration further enhanced the Xbp1s mRNA levels, but a statistically significant elevation of mRNA levels was only found in wildtype mice (p = 0.0021) 6 h after stroke." (PMID 31683519, 2019). "In addition, EPO is already used in clinical trials for many brain diseases including stroke, and in a clinical trial for extremely preterm infants (PENUT Trial)." (PMID 29973904, 2018). "This may also explain why EPO-only therapeutic approaches in stroke failed eventually in the clinic." (PMID 29423274, 2018). "In addition, in a rat model of transient focal cerebral ischemia and middle cerebral artery occlusion (MCAO), ECFCs primed with erythropoietin (EPO) were shown to have enhanced efficacy for reversing stroke injury." (PMID 30460233, 2018). "HIF-1α regulated downstream genes VEGF and EPO have direct neurotrophic effects and can prevent neuronal injury due to oxidative stress evoked by hypoxia or ischemia and can enhance recovery following stroke." (PMID 28106731, 2017). "This method has been reported to effectively bypass the blood-brain barrier (BBB) providing a direct connection of therapeutic proteins including EPO with the Central Nervous System (CNS) to treat neurodegenerative disorders such as Alzheimer’s and stroke while reducing systemic exposure." (PMID 28676085, 2017). "EPO has been shown to be effective in adult rodent models of transient focal ischemia and permanent ischemia by reducing infarct volume, and in embolic stroke by enhancing neurogenesis and angiogenesis and improving neurological function." (PMID 28134843, 2017). "This study provides a novel strategy of EPO+G-CSF combination therapy for stroke patients." (PMID 27043535, 2016). "Therefore, pharmacological treatment using multiple drugs such as erythropoietin (EPO) and granulocyte-colony stimulating factor (G-CSF) has been introduced in clinical trials for stroke patients." (PMID 27043535, 2016). "Based on these previous reports showing the therapeutic advantages of an EPO and G-CSF combination, we evaluated whether EPO+G-CSF combination therapy safely yielded hematological and functional improvement in stroke patients." (PMID 27043535, 2016). "IS stroke patients who were eligible for EPO therapy were enrolled into the study." (PMID 25888250, 2015). "This study aimed to evaluate the safety and efficacy of two consecutive doses of EPO (5,000 IU/dose, subcutaneously administered at 48 hours and 72 hours after acute IS) on improving the 90-day combined endpoint of recurrent stroke or death that has been previously reported." (PMID 25888250, 2015). "However, following reports of increased mortality (16% erythropoietin versus 9% placebo) in elderly patients after stroke, there were some concerns regarding safety of high-dose erythropoietin." (PMID 24783185, 2014). "Up-regulated serum and brain pro-inflammatory cytokines elicited by TBI or stroke were attenuated by treatment with rhEPO, although EPO administration enhanced BDNF up-regulation elicited by cerebral ischemia, but did not prevent inflammatory gene up-regulation (e.g., IL-1β, IL-6, TNF-α)." (PMID 23675319, 2013).
Stroke (continued). "Stroke upregulated Shh signal in SVZ neural progenitor cells and blockage of the Shh pathway with cyclopamine, a specific inhibitor of Smo, suppressed stroke-induced neural progenitor cell proliferation and attenuated EPO-increased neural progenitor cell proliferation." (PMID 24194700, 2013). "Indeed, a very recent paper showed a neuroprotective effect of EPO in an EPO-R knock out stroke animal model, which suggests that EPO's neuroprotective effect is not only through the EPO-R receptor; it probably involves the regulation of CBF." (PMID 22701364, 2012). "Indeed, Neuro/EPO IN showed the highest therapeutic window reported in preclinical stroke studies till now." (PMID 22701364, 2012). "Attention was drawn to the potential for EPO therapy in neurological diseases by the initial pilot study of 40 adult stroke patients that suggested high dose EPO administration was well tolerated in acute ischemic stroke and was associated with improved clinical outcome." (PMID 22567318, 2012). "In a pilot clinical trial EPO was safe in stroke patients and there was some evidence that EPO might improve outcome." (PMID 23109881, 2012). "Notably, EPO has been shown to be neuroprotective in animal models of stroke, spinal cord and peripheral nerve injury, and experimental autoimmune encephalomyelitis." (PMID 22046448, 2011). "Some of these preclinical findings could even be translated into clinical phase II studies, in which peripherally administered EPO exhibited beneficial potential in stroke and patients with MS." (PMID 22043313, 2011). "Thus, the development of EPO as a drug for CNS disorders such as stroke requires that the neurotrophin be re-engineered to cross the BBB." (PMID 21766022, 2011). "The first of these conditions to evaluate EPO as a potential therapy was human stroke." (PMID 21943500, 2011). "However, their local production is rapidly induced in response to acute hypoxia, as evidenced by the increased expression of EPO in cerebrospinal fluid (CSF) or postmortem brain tissue in humans with stroke and hypoxia." (PMID 21943500, 2011). "So far EPO and EPO analogues were widely tested in animal stroke models." (PMID 20459870, 2010). "Neuroprotection with intranasal Neuro-EPO (EPO, erythropoietin) has emerged as a multifunctional therapy that plays a significant role in neural survival and functional recovery in an animal model of stroke." (PMID 21103798, 2010). "Researchers have tried to profit from EPO as a neuroprotective agent in patients with stroke but it remains unclear how EPO acted neuroprotective." (PMID 21126346, 2010). "In a P10 rat stroke model, EPO increased the percentage of newly generated neurons as well." (PMID 21629441, 2010). "We showed here that G-CSF and EPO synergized to produce better functional recovery from stroke and limb ischemia than either factor alone, which might be due to much enhanced angiogenesis and significant relevant neuroprotection." (PMID 20404921, 2010). "Erythropoietin (EPO) is a neuroprotective agent utilized in stroke patients." (PMID 20948886, 2010). "Results of the more recent TREAT study suggest an intrinsic stroke-inducing capacity of EPO." (PMID 20459870, 2010). "The future for a further development of EPO as a stroke drug." (PMID 20459870, 2010). "We provide supporting evidence for the last theory, which encourages the use of EPO in stroke." (PMID 21126346, 2010). "Our in vivo and in vitro data indicate that EPO amplifies stroke-induced oligodendrogenesis that could facilitate axonal re-myelination and lead to functional recovery after stroke." (PMID 20552017, 2010). "The authors have pointed out that chronic systemic treatment with EPO may deteriorate outcome after stroke either because of elevated hematocrit or other chronic effects." (PMID 19079544, 2008).
Stroke (continued). "Furthermore, our results confirm the superior neuroprotective effect of a single dose of hS3 compared to EPO, which is in line with the higher expression patterns of hS3 mRNA observed in human stroke brains and supporting the concept of hS3 as a relevant endogenous neuroprotectant." (PMID 41602576, 2026). "It was reported that erythropoietin delivered via hydrogels to the cerebral cortex of stroke induced mice resulted in a significant increase in neurons, a decrease in inflammation, a reduction in stroke lumen size, and migratory neuroblast proliferation in the inferior ventricle." (PMID 38680508, 2023). "Since the FDA approved its use for patients with renal diseases over three decades ago, EPO has also been reported to exert multifaceted neuroprotective and neurorestorative actions in addition to its hematopoietic effects in both preclinical and clinical stroke studies." (PMID 35813499, 2022). "Despite the failed multicenter trial, there is a broad consensus that EPO remains a promising candidate for neuroprotective therapy, but extensive molecular and cellular preclinical investigations are needed prior to any potential clinical use in stroke patients." (PMID 35813499, 2022). "Human umbilical cord blood cells (hUCBCs) and erythropoietin (EPO) both have angiogenic and neurogenic properties in the injured brain, and their combined administration may exert synergistic effects during neurological recovery following stroke." (PMID 31024439, 2019). "Since both the EPO/EpoR and the JAK2/STAT3 pathways have been implicated as molecular targets for ischemic stroke prevention and treatment, the activation of both of these cell pathways and their downstream signaling cascades is recognized as a promising therapeutic approach for stroke patients." (PMID 28848617, 2017). "Therefore, we examined a novel approach of administering EPO and G-CSF concurrently, which has been known to exert synergistic effects in promoting angiogenesis, neurogenesis and functional recovery in experimental stroke models." (PMID 27043535, 2016). "The primary objective of this clinical trial was to evaluate the safety and efficacy of two consecutive doses of EPO (5,000 IU per dose, subcutaneously administered at 48 hours and 72 hours after acute IS, Epoetin beta; Roche) on improving the 90-day combined endpoint of recurrent stroke or death." (PMID 25888250, 2015). "Repeated administration of rHu-EPO high doses can activate the hematopoietic process with the potential risk of increasing blood viscosity, which might worsen the outcome after stroke either because of hematocrit elevation or other negative effects." (PMID 22701364, 2012). "EPO and its receptor are present in multiple systems of the body and can impact disease progression in the nervous, vascular, and immune systems that ultimately affect disorders such as Alzheimer’s disease, Parkinson’s disease, retinal injury, stroke, and demyelinating disease." (PMID 23109841, 2012). "Thus, sustained actively proliferating NG2 positive cells increased by EPO may play additional and as yet unidentified important roles in brain repair after stroke, which warrant further investigation." (PMID 20552017, 2010). "Indeed, the first proof-of-concept study on use of EPO in human acute ischemic stroke has already demonstrated that treatment of stroke patients with intravenous high dose EPO is not only well tolerated but is associated with improvement in clinical outcome at 30 days." (PMID 20142991, 2009). "The pronounced upregulation of hS3 mRNA under ischemia- and inflammation-related conditions (e.g., stroke, PPMS) emphasizes the functional importance of EPO alternative splicing in adapting to stress-related functional demands of the cell." (PMID 41602576, 2026). "In ALS brain sections, EPO mRNA expression exceeded hS3 mRNA expression, while in stroke and PPMS brains, hS3 mRNA expression surpassed EPO mRNA levels." (PMID 41602576, 2026).
Stroke (continued). "This study showed median EPO 24 h 808.6 pg/mL, with a median 24 h NIHSS of 6 and 76.6% accounted for moderate stroke." (PMID 38302546, 2024). "In a rat model of stroke, however, intraventricular infusions of EGF and erythropoietin (EPO) together promoted regeneration of the injured neocortex and reversed motor function deficits." (PMID 35756121, 2022). "Other mechanisms: Astrocytes can also release several neuroprotectants, including erythropoietin (EPO), VEGF, and glial-derived neurotrophic factor (GDNF), all of which can reduce ischemic neuronal damage after stroke." (PMID 35743941, 2022). "Hypoxic preconditioning of MSCs resulted in the up-regulation of HIF-1α, VEGF, erythropoietin (EPO), stromal-derived factor-1 (SDF-1), and C-X-C chemokine receptor type 4 (CXCR4), thus potentiating their pro-angiogenic capacities in stroke rodents." (PMID 35986375, 2022). "In patients with middle cerebral artery occlusion (MCAO), serum EPO levels peaked 2.6-fold at day 7 after MCAO and remained elevated until day 30 post stroke." (PMID 35250554, 2022). "In a rat model of stroke, combination therapy with UCB cell and EPO exerted synergistic effects on neurological recovery, characterized by neurogenesis and angiogenesis, compared to UCB or EPO monotherapy." (PMID 33246489, 2020). "Erythropoietin (EPO) is an hypoxia-induced cytokine and has neuroprotective activities in various models of brain injury, including hypoxia and stroke." (PMID 32733466, 2020). "Although EPO is a potential medication for acute ischemic stroke, its BBB penetration complicates the clinical usage of EPO via systemic delivery for stroke therapy." (PMID 30920178, 2019). "As a promising lead, erythropoietin (EPO) restores typical KCC2 expression in the hippocampus and brain following MIUH at E18 in rats, and in motoneurons after neonatal stroke." (PMID 29973904, 2018). "However, to confirm the hypothesis of hyperglycemia after hypoglycemia and stress response occurrence in brain ischemia following erythropoietin pretreatment, it is necessary to measure blood glucose before stroke induction and cortisol level in the early hours after the stroke." (PMID 30719249, 2018). "To explore the potential of MK-X to be developed as a drug for stroke treatment, we subjected rats to MCAO for 2 h followed by reperfusion for 24 h with single injection of saline, EPO, or MK-X." (PMID 28817120, 2017). "There were significant differences between vehicle and GSK360A for EPO and VEGF levels 24 hours after tMCAO stroke (p<0.01)." (PMID 28880966, 2017). "The administration of erythropoietin increases EPC mobilization and promotes vascular remodeling, as well as improves neurological outcome after stroke." (PMID 29201537, 2017). "Findings of previous studies have demonstrated that EPO can cross the BBB and the systemic administration of EPO improved neurological function of a rat model of stroke." (PMID 24939444, 2014). "Erythropoietin (EPO) can enhance the neurogenesis and angiogenesis via BDNF and VEGF in rat stroke model." (PMID 24719869, 2014). "Previous studies demonstrated that the epicortical delivery of EPO and HGF enhance neurogenesis in the SVZ in mouse models of stroke." (PMID 23093979, 2012). "EPO and EPOR also induce neurogenesis after stroke, early during embryonic development and in vitro via Jak2/Stat3 and PI3K/AKT pathway activation." (PMID 21777449, 2011). "EPO readily penetrates the blood-brain barrier (BBB) and recent phase II studies showed that peripherally administered EPO is beneficial in stroke and multiple sclerosis patients." (PMID 22046448, 2011). "Hypoxia rapidly induces expression of brain EPO as evidenced by the increased expression of EPO in cerebrospinal fluid (CSF) or postmortem brain tissue in humans with traumatic brain injury, SAH, stroke and hypoxia." (PMID 20142991, 2009).